DCN (decorin)
Diseases named in the same sentence as DCN in open-access papers (continued):
Sharing a sentence is not in itself a finding about the gene and the disease.
tumor (continued). "Decorin expression in different tumor stroma has not been extensively studied and reported findings are somewhat contradictory." (PMID 24634138, 2014). "Considering the postulated role of decorin as a tumor suppressor, we expected to find it expressed in normal tissues but not in the tumor stroma." (PMID 24634138, 2014). "As we screened the samples for the immunoreactivity for another, very similar SLRP to decorin, namely biglycan, we found that the tumour areas negative for decorin were positive for biglycan immunoreactivity." (PMID 24146840, 2013). "Reduced expression of decorin in MB49-I-shDcn1 and MB49-I-shDcn2 did not modify the amount and relative proportions of immune cells infiltrating the tumour, thus suggesting that decorin does not affect directly anti-tumoural immune response." (PMID 24142880, 2013). "Decorin is a member of the small leucine-rich proteoglycan gene family and it can impede tumor growth, but its molecular basis has not been elucidated." (PMID 23296269, 2013). "In muscle tissues, DCN appears to be preferentially transcribed from a promoter that is not expressed in normal and tumoural tissues." (PMID 24142880, 2013). "The results indicated that disruption of the decorin gene does not lead to spontaneous development of tumours, but lack of decorin is permissive for tumourigenesis." (PMID 24146840, 2013). "In this study, decorin-expressing oncolytic Ad significantly reduced ECM components within the tumor tissues while normal tissue adjacent to the tumor was not affected." (PMID 23898462, 2013). "Although these different promoters induce expression of the same protein, their different use in the two tissues allows us to rule out that decorin overexpression in tumours is due to muscle infiltration." (PMID 24142880, 2013). "In Group C, tumor cells exhibited no decorin immunoreactivity, and decorin was only expressed by some mesenchymal cells, with the strongest staining observed in the ECM at the border of the tumor." (PMID 20092659, 2010). "Moreover overexpression of decorin also plays a role in TGF-β by inhibiting its synthesis and bioactivity, thus entering another important CRC development pathway as a tumour suppressor gene." (PMID 19678923, 2009). "So far, SLC26A3, DCN and TPM1 genes have been suggested to have tumour suppressor properties." (PMID 19678923, 2009). "In previous studies, TaqMan quantitative PCR was utilized to confirm the expression of several genes (decorin, IGFBP2, Thrsp, Sncg, SerpinG1) in MIN-O and tumor pairs and showed that this data correlated with the direction and fold change of the microarray data." (PMID 17147824, 2006). "The tumorigenesis of SPN may be closely related to oxygen metabolism, MYC targets, and DNA repair;SPN tumor cells may originate from pancreatic endocrine progenitor cells;NOV, DCN were nominated as primary and S100A10, MGP as recurrent SPN marker genes, respectively." (PMID 40312910, 2025). "Decorin and lumican can suppress growth factor signaling (e.g., TGF-β and EGFR), while biglycan may promote inflammatory signaling through TLR2/4, underscoring their dual tumor-suppressive and tumor-promoting roles." (PMID 41228294, 2025). "Additionally, COL1A1 and FBLN1 were previously used as markers for canine tumor or fibroblast cells, and MMP2 and DCN as markers of mesenchymal-like cells in human cancers, with the latter also being a top differentially expressed gene in our canine STS sample." (PMID 41208961, 2025). "Notably, DCN + cells were generally absent from the small PDGFRB+/SMA + vessels within the tumor cell nests." (PMID 40841830, 2025). "In addition, various investigations conducted on cancer cells suggest that DCN does not inhibit but rather promotes apoptosis in the tumor tissue." (PMID 38786104, 2024).
tumor (continued). "To begin to determine what might be the role of CCN1 expression by CAFs, we used CAF single-cell expression data to identify a group of six genes (PDGFRA, COL1A1, DCN, TAGLN, COL6A3, and LPAR1) that strongly correlated with CCN1 expression, yet were minimally expressed in other tumor cell types." (PMID 38363129, 2024). "Furthermore, QZACP induced irreversible cell cycle arrest in stressed tumor cells by up-regulating the expression of p21 and promoting the secretion of PASP factors (decorin, CXCL14, and Wnt family member 2) within tumor cells after recruiting NK and CD8+ T cells." (PMID 39206194, 2024). "Indeed, it has been found that DCN level was expressed in the stroma of normal tissues while it was significantly reduced or absent in the corresponding tumors, which facilitated tumor growth and progression." (PMID 38667295, 2024). "For instance, ferroptotic PDAC cells can release KRAS-G12D protein, which drives tumor growth through polarization of macrophages, whereas the release of high mobility group box protein B1 (HMGB1) and membrane proteoglycan decorin (DCN) can stimulate anti-tumor cytotoxic T cell responses." (PMID 37601110, 2023). "Analysis of a large genomic patient dataset revealed that the SLRPs lumican, fibromodulin and decorin as well as COL1A1 and COL6A1 all correlate with good overall survival in SHH MB patients; suggesting that the presence of this ECM shell in SHH tumours may be a reliable biomarker of good outcome." (PMID 36631900, 2023). "In addition, decorin expression in recurrent or metastatic STS was lower than in the primary lesions, supporting a hypothesis that these secondary tumours have a more aggressive phenotype than the original primary tumour." (PMID 37104411, 2023). "However, unlike decorin, endorepellin, endostatin and biglycan foster tumour angiogenesis in metastatic cancer via upregulating VEGFA levels and VEGFA–VEGFR2 signalling." (PMID 34982945, 2022). "Moreover, in the subcutaneous tumor transplantation model of NCG mice, we found that the combined treatment of CAR-T and OAV-Decorin could effectively inhibit tumor growth and greatly improve the survival percentage of the mice." (PMID 34977339, 2022). "Differential gene expression analysis by Seurat34,35 identified 160 genes uniquely upregulated in tumor cells compared with TAF and normal kidney, including genes previously reported (e.g., GPNMB8, SQSTM1/p6236, MMP237, PTGDS38) and genes involved in tumor metastasis (e.g. MMP11, MDK, DCN, PDPN)." (PMID 36028490, 2022). "On the other hand, decorin carried by OAV improved the permeability of tumor tissues and changed the tumor immunosuppressive microenvironment by boosting the inflammatory immune status, so that CAR-T or lymphocytes could infiltrate into tumor tissues more and played a better antitumor affect." (PMID 34977339, 2022). "While DPT triggers a small diameter collagen assembly, decorin notably delays fibril formation, suggesting the role of these two molecules in the regulation of the assembly and turnover of collagen in the ECM greatly influencing cell behaviour in the tumour microenvironment." (PMID 36012487, 2022). "Several studies reported that a lack of DCN leads to spontaneous tumour development." (PMID 35052821, 2022). "Interestingly, both FGF and VEGF are potent pro-angiogenic factors and thus—having in mind the anti-angiogenic role of decorin—this FGF- and VEGF-induced decorin down-regulation may further promote vascularization favoring tumor growth." (PMID 33924197, 2021). "The highest tumor count was observed in mice with no decorin production." (PMID 32477937, 2020). "Mechanically, DCN binds to EGFR/ErB2 extracellular functional domains and triggers mitogen-activated protein kinase activation and the increase of cytosolic Ca2+, which accelerates cell cycle arrest and induces intrinsic cell apoptosis, eventually leading to tumor cell growth inhibition." (PMID 31583243, 2019).
tumor (continued). "In terms of cancer, DCN has been shown to have a negative impact on tumour angiogenesis." (PMID 30834271, 2019). "Markedly higher quantities of CD8+ T cells were found in RdB/IL12/DCN-treated tumors compared with tumors treated with PBS, RdB, RdB/IL12 or RdB/DCN (P < 0.01), suggesting that the decreased population of Treg cells correlated with enhanced infiltration of CD8+ T cells into tumor tissues." (PMID 28002796, 2017). "Moreover, data has revealed that the effect of decorin is specific for tumor cells, as neither apoptosis nor growth inhibition was observed in non-cancerous cells." (PMID 28067804, 2017). "Similarly to DCN, LUM is reported to mediate tumor suppression." (PMID 26230845, 2015). "However, a recent study indicated that the expression of only decorin, but not the other related SLPRs such as asporin and biglycan, varied between tumor and normal tissues." (PMID 26379028, 2015). "Identification of the signaling pathways and mechanisms regulating TGFβ1-induced decorin down-regulation in CAF/MF in vitro and in vivo will provide a rationale for new therapeutic options aimed to neutralize the oncogenic role of TGFβ1 as a repressor of the decorin tumor suppressive functions." (PMID 25526025, 2014). "We thus hypothesized that MB49-I-derived decorin acts by interacting with other cells in the tumour microenvironment, but we had not observed obvious differences in the immune microenvironment generated by decorin-impaired MB49-I cells." (PMID 24142880, 2013). "Immunohistochemistry showed a strong membranous and cytoplasmic expression of decorin by epithelial tumour cells together with a weaker expression by stromal cells whereas normal urothelial cells did not express DCN in agreement with our transcriptomic data for normal urothelium samples." (PMID 24142880, 2013). "Molecular subtype analysis indicated that high expression of DCN in malignant epithelial cells is a predictor of decreased OS (HR: 2.33 vs. low expression p = 0.002) only in luminal B subtype tumours as is high expression of DCN in the benign peri-lesional stroma (data not shown)." (PMID 22363530, 2012). "Lastly, we found no deletions of the DCN gene using the real-time PCR method, showing that either methylation of promoter or suppression by trans-activating elements must be responsible for DCN underexpression in a tumour." (PMID 19678923, 2009). "Hence, rather than exerting a direct anti‐tumour effect, DCN expression in B cells might reflect an immunosuppressive, pro‐tumorigenic phenotype." (PMID 41392017, 2026). "Moreover, while DCN levels in serum did not correlate with DCN expression in resected tumours, a comprehensive mapping of the tumour landscape unveiled variations in its compartmental and cellular distribution which could be of potential clinical importance." (PMID 41392017, 2026). "Our previous studies showed that the lack of decorin favors primary hepatocarcinogenesis, which results in higher tumor incidence, however it was a further question whether the addition of the proteoglycan is able to counteract primary hepatocarcinogenesis evoked by TA." (PMID 32477937, 2020). "Moreover, DCN might be one of the regulators of the synthesis of the ECM components and expression of collagenase, inhibitor of collagen I maturation which contributes to angiogenesis in the tumor." (PMID 33322258, 2020). "Moreover, DCN inhibits hypoxia inducible factor-1α (HIF-1α) and VEGFA via a Met-dependent pathway and induction of the endogenous angiostatin proteins thrombospordin-1 and tissue inhibitor of metallo-proteinases-3 (TIMP3) to promote anti-angiogenesis and prevention of tumour growth and metastasis." (PMID 29435195, 2018). "Moreover, decorin, but not biglycan, could inhibit the metastasis of the targeted tumor cells through transgenic delivery." (PMID 26379028, 2015).
tumor (continued). "Importantly, intratumoral administration of decorin-expressing oncolytic Ad to the primary tumor site substantially reduced the formation of B16BL6 melanoma pulmonary metastases in mice, indicating that this approach is capable of inducing a systemic anti-tumor immune response." (PMID 23898462, 2013). "TCCSUP cells did not form tumours when injected subcutaneously in immunodeficient mice (up to 107 cells/flank without or with matrigel, in nude or scid mice) so we could not address the pro-tumoural role of DCN in vivo in this model." (PMID 24142880, 2013). "Analysis of TCGA-LIHC data revealed elevated expression of SOX9, DCN, GPC3, and B3GNT3 in tumor tissues versus non-tumor counterparts." (PMID 41268541, 2025). "Due to lack of space, we will refer to decorin (SLRP) and versican (hyalectan), two extracellular proteoglycans with often contradicting functions in tumor biology." (PMID 40542654, 2025). "Immunohistochemical analysis of CD56 expression in tumor tissues revealed more CD56-positive staining in the NK and rAd.DCN + NK groups, with no CD56-positive staining in the CON or rAd.DCN groups." (PMID 39482550, 2024). "This study showed that recurrence following surgery was more likely if the tumour had a high level of staining for VEGF and/or did not stain for decorin." (PMID 37104411, 2023). "The results prove that the expression levels of B3GALT6, DCN, FBP2 and GYS2 are lower in tumor samples and higher in normal tissue samples." (PMID 32489319, 2020). "DCN expression was decreased in RCC tissues compared to adjacent noncancerous tissues and was highly correlated to tumor size." (PMID 33542901, 2020). "The expression levels of B3GALT6, DCN, FBP2 and GYS2 are lower in tumor samples and higher in normal tissue samples." (PMID 32489319, 2020). "Significantly increased decorin and SMA levels were observed in NAT samples compared to normal liver (p < 0.001 for both decorin and SMA) and tumor stroma (p < 0.05 for SMA)." (PMID 32477937, 2020). "Unlike endorepellin, which has no direct effects on cancer cells, decorin also binds EGFR and Met receptors expressed on tumor parenchyma and inhibits tumor growth and development through stunting proliferation and angiogenesis while activating mitophagy." (PMID 33020183, 2020). "The high % decorin levels in the normal brain are due to expression in both the nucleus and cytoplasm, similar to PDGFR-α, and conversely the majority of tumor cells had negative nuclei." (PMID 26248280, 2015). "Mean TMA protein expression levels of HSP90B1 and DCN showed the strongest statistical association with presence of LN metastasis being significantly higher in LN positive tumours relative to LN negative tumours (HSP90B1 p = 0.049; DCN p<0.001)." (PMID 22363530, 2012). "Since decorin did not regulate MB49-I cells proliferation, we hypothesized that it affects the tumour environment." (PMID 24142880, 2013). "However, decorin is endogenously expressed by tumour cells and is not anti-proliferative in our model since in vitro growth of MB49-I was not increased by inhibition of decorin." (PMID 24142880, 2013). "Because decorin has been shown to inhibit the epithelial mesenchymal transition (EMT), this increase in fibroblast-like cells is most likely the result of decorin’s capability to normalize the tumour tissue histology rather than to promote more aggressive mesenchymal phenotype typical for MBC." (PMID 28653173, 2017).
cancer (209 papers, 2008 to 2026). A tumor composed of atypical neoplastic, often pleomorphic cells that invade other tissues. "DCN is secreted by cancer-associated fibroblasts, an immune cell type found to be abundant across all four clusters, further establishing its role in modulating the TME." (PMID 40349011, 2025). "Shared pseudotemporally correlated genes between both integrated datasets included genes associated with proliferation (CENPF and TOP2A), cancer‐associated fibroblasts (DCN and COL1A1) and neurodevelopment (HMGB2 and NPAS3)." (PMID 39836549, 2025). "Next, since cancer stem cells (CSCs) play a critical role in cancer recurrence and resistance to drugs, we sought to assess the effect of DCN-deficient fibroblasts on the response of BC cells to chemotherapeutic drugs." (PMID 38667295, 2024). "Decorin expressed by cancer-associated fibroblast (CAF) has been shown to be important in the inhibition of HCC through a synergistic inhibition with integrin β1 of HCC cell invasion and migration." (PMID 37049569, 2023). "Cancer-associated fibroblasts were clearly divided into three clusters, and their marker genes were DCN, FAP and RGS5." (PMID 37963845, 2023). "This study is designed to investigate the diagnostic role of the plasma DCN levels and evaluate any association with expression levels in cancer tissue, the progression of the disease, and the characteristics of the patients." (PMID 34884232, 2021). "The interaction of decorin with TGF-β causes strong inhibition of proliferation in various cancer cell lines, presumably by decorin-binding activity on TGF-β isoform 1 (TGF-β1), thereby sequestrating it in the ECM and limiting its bioactivity." (PMID 34917515, 2021). "Previous studies have shown that DCN is expressed by cancer-associated stromal cells or by cancer cells." (PMID 33452400, 2021). "Its antitumorigenic role though is unequivocal, having rendered decorin expression in the cancer-associated stroma a molecular predictor for the prognosis of the disease." (PMID 33924197, 2021). "Our findings showed that targeting cancer-associated fibroblast-related decorin is not only a promising strategy for inhibiting HCC vascular invasion and metastasis but also provides insight into the clinical treatment of patients with PVTT." (PMID 34504839, 2021). "Some cancer-related mechanism of these molecules has been reported: DCN encodes decorin, a class I SLRP that participates in collagen fibrillogenesis." (PMID 34987579, 2021). "In their experiments, TGFβ1 was identified as the main inducer of decorin repression in cancer associated fibroblasts." (PMID 32477937, 2020). "DCN has been implicated to play a role in the development and progression of cancer and a substantial amount of work has been published on its therapeutic anticancer effects." (PMID 26697491, 2015). "Some of these cancer-related genes were associated with processes occurring in the extracellular matrix and related to DCN: CXCR4/CXCL12 axis, SELP, vWF, COL3A1, SCARA, SPARCL1." (PMID 26437222, 2015). "More precisely, soluble decorin induces the expression of Peg3, a transcription factor usually silenced in cancer and causes inhibition of endothelial tubulogenesis and cell migration." (PMID 26056582, 2014). "Carcinoma cells in effusions showed down-regulated ECM encoding molecules such as decorin, fibronectin, collagens I, XXII and V, concomitantly with the downregulation of the ECM-binding receptors, integrins α5 and α7." (PMID 19680458, 2010). "Of the 29 enriched proteins, only two are described as inhibiting cancer cell growth and migration, as well as causing lysosomal/mitochondrial dysfunction and increasing apoptosis: cystatin C (through its inhibition of cathepsins) and decorin." (PMID 41300368, 2025). "Thus, the activation of TGF-β signaling in certain cancers is driven, in part, by the loss of decorin expression." (PMID 38675493, 2024).